KRAS (KRas proto-oncogene, GTPase)
Diseases named in the same sentence as KRAS in open-access papers (continued):
Sharing a sentence is not in itself a finding about the gene and the disease.
colorectal cancer (continued). "The highest frequency of gene rearrangements was seen in KRAS/NRAS/BRAF wild-type colorectal carcinomas (53/204 (26%))." (PMID 37686416, 2023). "With regard to the carcinogenesis, it is noteworthy that the colorectal carcinoma of the index patient carried pathogenic APC and KRAS mutations as observed in conventional sporadic and FAP- and MAP-related colorectal carcinomas." (PMID 35675019, 2023). "Despite being in the same pathway, mutations of KRAS and BRAF in colorectal carcinomas (CRCs) determine distinct progression courses." (PMID 37870961, 2023). "The best example of TSA is KRAS due to its high mutation rate in numerous cancers, such as pancreatic ductal adenocarcinoma (PDAC) and colorectal carcinoma (CRC)." (PMID 38250839, 2023). "We also evaluated the potential for the simultaneous use of 89Zr-matuzumab PET/CT and nimotuzumab-PEG6-DM1 for biparatopic imaging and therapy, respectively, in EGFR-positive KRAS mutant colorectal cancer models." (PMID 36145664, 2022). "We also analyzed 508-case TCGA and 63-case CPTAC colorectal cancer cohorts for all members of the GALNT enzyme family, the mucin family, as well as KRAS and BRAF mutations." (PMID 35692787, 2022). "The downregulation of B3GNT6 mRNA expression in colorectal cancer tissues is related to CIN status, KRAS mutation, and proteasome pathway." (PMID 35387659, 2022). "The small molecule C19 inhibits the viability and proliferation of colorectal cancer cells in vitro and in vivo, through decreased activation of KRAS and, therefore, inhibition of phosphorylation of downstream kinases such as AKT and ERK." (PMID 35631681, 2022). "Not only PDAC, other KRAS-mutant cancers, such as colorectal cancer are also sensitive to co-target of autophagy essential gene Atg7 and RAF kinases, the subset of KRAS signaling." (PMID 34459894, 2022). "We reported that miR-143 has a significant tumor-suppressive effect on DLD-1 human colorectal cancer cells in vitro and in vivo by silencing the KRAS signaling network." (PMID 35566730, 2022). "Tetrac induces an antiproliferative effect by suppressing ERK1/2 activation in colorectal cancer cell lines with different KRAS statuses." (PMID 36005485, 2022). "To date, the CE-IVD IdyllaTMKRAS Mutation Test and the IdyllaTMNRAS-BRAF Mutation Test have been developed to detect KRAS, NRAS, and BRAF mutations in colorectal cancer patients." (PMID 35474548, 2022). "COLO320DM is an EGFR-negative human colorectal cancer cell line with wild-type KRAS/BRAF, which is an ideal cell model for generating stable EGFR mutant cell lines." (PMID 35907884, 2022). "MiR-31, on the other hand, has oncogenic potential in other cancers, such as lung and colorectal cancers, because the KRAS can increase the level of miR-31 by stimulating its promoter." (PMID 36247409, 2022). "In colorectal cancer, amplifications in cytoband 20q13.33 were associated with early tumoral stages and mutations in APC and KRAS." (PMID 36232418, 2022).
colorectal cancer (continued). "In fact, one of the genes related to cryptorchidism and, as a consequence, to TGCTs is KRAS, which has been observed to be enhanced by furin in colorectal cancer." (PMID 35406405, 2022). "For example, the frequencies of APC and CDKN2A gene abnormalities in small intestinal adenocarcinoma are lower than in colorectal cancer, but KRAS gene abnormalities are observed as frequently as in colorectal tumors." (PMID 35566730, 2022). "Another small-molecule KYA1797K, was identified as a potent inhibitor of cetuximab-resistant KRAS-driven colorectal cancer." (PMID 35409064, 2022). "- Inhibition of tumour growth in a colorectal cancer patient-derived xenograft model and KRAS G12C SCLC and NSCLC patient-derived xenograft models." (PMID 35251972, 2022). "In colorectal cancer samples, the author observed a trend towards mutual exclusivity for BRAF and KRAS mutations." (PMID 36275468, 2022). "Nevertheless, a recent study has also shown that a cotreatment with β-elemene—a natural product isolated from the Chinese herb Curcumae rhizome—and Cetuximab sensitizes KRAS mutant metastatic colorectal cancer cells by inducing ferroptosis." (PMID 36012290, 2022). "A straightforward example of this is the indication of EGFR antibodies cetuximab and panitumumab only for KRAS wild type colorectal cancer." (PMID 36284306, 2022). "Five CDx devices are approved for KRAS wild type (exons 2, 3, and 4; codons 12 and 13) for use in colorectal cancer." (PMID 35689144, 2022). "Mutant KRAS is a key driver in colorectal cancer (CRC) and promotes Myc translation and Myc-dependent stress adaptation and proliferation." (PMID 35307764, 2022). "The aim of the present study was to investigate self‐reported diabetes status in relation to molecular tumor traits in colorectal cancer (BRAF and KRAS mutations, MSI status and CpG island methylator phenotype [CIMP])." (PMID 35383926, 2022). "Among the subtypes of gene KRAS, KRAS G12D is a common submutation, found in colorectal cancer, pancreatic cancer, and non-small cell lung cancer." (PMID 35574466, 2022). "For KRAS wild-type colorectal cancer, cetuximab combined with chemotherapy as first-line therapy can significantly improve survival time." (PMID 36212504, 2022). "The IdyllaTMKRAS and NRAS-BRAF Mutation Tests have been developed for the qualitative detection of mutations in KRAS, NRAS and BRAF genes, facilitating the genomic profiling of patients with colorectal cancer." (PMID 35474548, 2022). "For example, the KRAS G13D–mutated breast cancer cell line (MDA-MB-231) and colorectal cancer cell line (NCI-H747) were sensitive to the SHP2 inhibitors SHP099 and TNO155, respectively." (PMID 35462913, 2022). "An immunocytochemical study found that the administration of 10 μM quercetin reduces p21 KRAS in colon cancer cells and in initial colorectal cancer." (PMID 35409064, 2022). "JUN is involved in the transcriptional activation of USP28 in colorectal cancer (CRC) cells by activated KRAS." (PMID 36004808, 2022). "The results showed that compared with KRAS wild-type colorectal cancer cell line, KRAS mutant colorectal cancer cell line showed significant upregulation of ACSL4." (PMID 35910359, 2022).
colorectal cancer (continued). "Prognosis of KRAS-mutant versus other genomic cohorts of lung, pancreatic, and colorectal cancer were assessed using a real-world clinicogenomic database." (PMID 36494601, 2022). "An artificial small RNA sequence (MIRTX) is found to have a potential therapeutic strategy in KRAS-mutant colorectal cancer." (PMID 35887337, 2022). "In colorectal cancer, RAS mutations have been detected in 45% of patients, with KRAS being the most commonly mutated one." (PMID 35139853, 2022). "The data reviewed in the current manuscript show the close interaction between KRAS oncoprotein and several non-coding RNAs, particularly in the context of lung, pancreatic and colorectal cancers." (PMID 35139853, 2022). "The phase II portion of CodeBreak100 for KRAS G12C-mutant colorectal cancer included 62 patients with prior fluoropyrimidine, oxaliplatin, and irinotecan treatment." (PMID 36284306, 2022). "We identified compensatory activation of SRC family kinases using reverse‐phase protein array (RPPA) analysis to profile the protein and phosphoprotein expression of KRAS mutant colorectal cancer cell lines treated with MEK inhibitors." (PMID 34856074, 2022). "Kirsten rat sarcoma viral oncogene homolog (KRAS)-mutated colorectal cancer (CRC) seems to have a different biological behavior and therapeutic approach compared with non-KRAS mutated CRC." (PMID 35884381, 2022). "HT-29 cells overexpress EGFR and are representative of wildtype-KRAS and BRAF-mutated tumours, which have been reported in approximately 5-15% of patients with colorectal cancers." (PMID 36591314, 2022). "In summary, our integrated proteogenomic characterization revealed new molecular subtypes and therapeutic opportunities for targeting signaling proteins, phosphosites, and genomic alterations in KRAS-mutant colorectal cancer." (PMID 35836817, 2022). "Many cancer biomarkers have been elucidated, such as KRAS in colorectal cancer, human epidermal factor receptor 2(HER2) in breast cancer, and EGFR in lung cancer." (PMID 36589754, 2022). "A combination of adagrasib with cetuximab, an EGFR-directed monoclonal antibody, was explored in 32 patients with KRAS G12C colorectal cancer." (PMID 36284306, 2022). "The SHP2 inhibitor developed by Novartis, TNO155, inhibits MAPK signaling and enhances the efficacy of KRAS (G12C) inhibitors against KRAS (G12C) lung and colorectal cancers." (PMID 35922812, 2022). "Currently, the anti-EGFR mAbs cetuximab and panitumumab are used in the treatment of metastatic KRAS wild-type colorectal cancer patients." (PMID 35035479, 2022). "Recently, specific targeting of KRAS mutants with small molecules revived the hopes for successful therapies for lung, pancreatic, and colorectal cancer patients." (PMID 35014625, 2022). "At oral doses of 25 mg/kg daily, RMC-6236 showed encouraging activity and durable responses in murine studies with KRAS G12X lung cancer, pancreatic cancer and colorectal cancer xenografts." (PMID 36284306, 2022). "In KRAS-mutant colorectal cancer cells, inhibition of the Nrf2/HO-1 axis contributed to the promotion of ferroptosis induced by RSL3, a GPX4 inhibitor." (PMID 35350242, 2022). "Within this scope, we focused on a severe phenotype of colorectal cancer with APC loss and mutated KRAS (adenocarcinoma state)." (PMID 35465155, 2022). "KRAS and NRAS mutations are known to be the most frequent actionable mutations observed in colorectal cancer." (PMID 35474548, 2022).
colorectal cancer (continued). "Kirsten rat sarcoma viral oncogene (KRAS) is an intracellular membrane-bound GTPase enzyme that is highly mutated in non-small cell lung cancer (NSCLC), colorectal cancer, and most solid tumors (e.g., pancreatic adenocarcinoma)." (PMID 36614109, 2022). "In a report of 46 patients with KRAS G12C colorectal cancer, the ORR with adagrasib was an encouraging 22% with a disease control rate of 87%." (PMID 36284306, 2022). "Second, we were not able to evaluate CMS categories or genomic alterations such as microsatellite instability and KRAS and BRAF mutations that are important for precise characterization of colorectal cancer." (PMID 36052235, 2022). "Wnt/β-catenin and RAS-MAPK signaling are the central pathways for KRAS, and APC mutation causes drug-resistant colorectal cancer (CRC)." (PMID 35409064, 2022). "Although KRAS is one of the most frequently mutated genes in colorectal cancer (CRC), only 3–4% of all patients with metastatic CRC exhibit a KRAS G12C mutation." (PMID 35505999, 2022). "We also interrogated a real-world clinicogenomic database (CGDB) to assess prognostic implications for KRAS mutated subsets compared to other genomically defined cohorts of NSCLC, colorectal cancer (CRC), and pancreatic ductal adenocarcinoma (PDAC)." (PMID 36494601, 2022). "In clinical practice, EGFR-targeted therapy (cetuximab) can improve the overall survival (OS) in KRAS wild type colorectal cancer patients, which is an important method of targeted therapy for colorectal cancer patients." (PMID 35319011, 2022). "This suggests that overexpression of HER2 is more likely to occur in patients with left hemicolorectal cancer and KRAS/NRAS/BRAF WT colorectal cancer." (PMID 35365123, 2022). "We see great responses in KRAS-driven lung cancer, but hardly any in colorectal cancer, which mirrors the BRAF-driven melanoma versus colorectal cancer differences." (PMID 34498671, 2022). "In this manner, the IdyllaTM mutation tests were validated for the detection of clinically significant KRAS, NRAS, and BRAF mutations in FFPE samples from colorectal cancer patients." (PMID 35474548, 2022). "Mutations in PIK3CA are the most frequent mutations in the receptor tyrosine kinase-initiated pathways in colorectal cancers with BRAF mutations, as the even more frequent KRAS mutations are mutually exclusive with BRAF mutations." (PMID 36295658, 2022). "Cumulatively, circ_GLG1/miR-622/KRAS axis has been found to participate in the pathogenesis of colorectal cancer." (PMID 35139853, 2022). "Corroborating our findings that sEV miR-3182 abundance is a result of cancer-specific mutations, one study described increased abundance of miR-3182 in sEVs derived from mutant KRAS colorectal cancer cells compared to parental and wild-type KRAS cells." (PMID 35008424, 2022). "AMG-510 (entry 15) is an experimental KRAS inhibitor that is under study for the treatment of KRAS G12C mutant non-small cell lung cancer, colorectal cancer and appendix cancer." (PMID 35337149, 2022). "Within the one carbon pathway, limiting dietary methionine reduced tumorigenesis in chemotherapy-resistant KRAS-driven colorectal cancer and radiation-resistant KRAS-driven soft tissue sarcoma." (PMID 36295863, 2022).
colorectal cancer (continued). "The authors of this study also reported higher levels of phosphorylated p65 in neoplastic tissue from mutant KRAS colorectal cancer samples." (PMID 35359456, 2022). "It is with this purpose that KRAS G12D organoids have been created from wild-type colorectal cancer specimens to study the response to EGFR-RAS-ERK pathway inhibition, which is ineffective in RAS-mutated cancers." (PMID 35954355, 2022). "Some of the commonly identified mutations associated with targeted therapies include, e.g., mutations in BRAF in cutaneous melanoma; KRAS, BRAF, and NRAS in colorectal cancer; and EGFR mutations and ALK and ROS1 gene rearrangements in lung adenocarcinomas." (PMID 35627184, 2022). "In colorectal cancer, PIK3CA is mutated in 20% to 25% of cases and is the second most commonly mutated oncogene after KRAS." (PMID 36295658, 2022). "For example, mutations of KRAS and NRAS predict resistance to anti-EGFR antibodies in colorectal cancers, and patients with lung adenocarcinoma that harbor EGFR mutations or ALK rearrangements have shown remarkable efficacy in relevant targeted drug therapy." (PMID 36741696, 2022). "Looking for metabolic-associated vulnerabilities is a promising approach for therapeutic intervention in KRAS-mutant colorectal cancer." (PMID 35803966, 2022). "Exosomes of the colorectal cancer cell line with mutant KRAS (DKO-1, DLD-1) showed a microRNA expression profile significantly different from exosomes of cells with wild-type KRAS (DKs-8)." (PMID 36012109, 2022). "On the one hand, the role of KRAS mutations in the occurrence and development of PDAC has been basically clear, while on the other, the medicinal properties of KRAS gene have achieved a breakthrough in solid tumors such as lung cancer and colorectal cancer." (PMID 36118526, 2022). "Resent research has reported that the blockade of Nrf2/HO-1 signaling promotes RSL3-induced ferroptosis in KRAS mutant colorectal cancer." (PMID 35422066, 2022). "We aimed to investigate the frequency and clinicopathological characteristics of double-mutant colorectal carcinoma and its differences from KRAS/BRAF single-mutant colorectal carcinoma using bioinformatics tools." (PMID 35280113, 2022). "Patients with metastatic KRAS wild-type colorectal carcinoma with primary tumors originating in the left-sided colon can be treated with cetuximab or panitumumab monotherapy." (PMID 35035479, 2022). "Sex, histological type, histological grade, microsatellite instability, and tumor mutation burden of the patients harboring KRAS-mutant, BRAF-mutant, and double-mutant colorectal carcinoma varied significantly." (PMID 35280113, 2022). "Previously, it was reported that RAD21 overexpression is a marker for poor prognosis in breast, bladder, KRAS mutant colorectal carcinomas, and NSCLC." (PMID 35227290, 2022). "Aside from KRAS (colorectal cancer, amplified in 1% of TCGA cases), MCL1 (lung squamous carcinoma, 4.7%) and BRAF (melanoma, 4.1%) amplifications have also been implicated as oncogenic alterations in OncoKB." (PMID 34313788, 2021). "Transfer of oncogenic KRAS promotes formation of TNTs by regulating the ERK pathway in colorectal cancer." (PMID 34921322, 2021). "High-dose vitamin C selectively kills KRAS-mutant colorectal cancer cells, which upregulate GLUT1, and recently a synergistic effect was demonstrated with fasting-mimicking diets in KRAS-mutated cancers." (PMID 33803326, 2021). "If the response of duodenal adenocarcinoma was similar to that of colorectal cancer, angiogenesis inhibitors would be better than EGFR inhibitors for the treatment of duodenal adenocarcinoma with KRAS mutation." (PMID 34797780, 2021).